GTF3C3 (general transcription factor IIIC subunit 3)
Description:
Involved in RNA polymerase III-mediated transcription. Integral, tightly associated component of the DNA-binding TFIIIC2 subcomplex that directly binds tRNA and virus-associated RNA promoters.
Synonyms: TFIIIC102; TFiiiC2-102; NEDFBS; TFIIICgamma
Tractability: PROTAC: ubiquitination databases record sites on it; its protein half-life has been measured.
Gene: Protein-coding gene on chromosome 2 (196,761,062 to 196,799,725, reverse strand). Ensembl gene ENSG00000119041.
Subcellular location: Nucleus
Subcellular location (Human Protein Atlas): Nuclear membrane; Nucleoplasm; Nucleoli fibrillar center
Pathways (Reactome):
Gene expression (Transcription): RNA Polymerase III Abortive And Retractive Initiation; RNA Polymerase III Transcription Initiation From Type 1 Promoter; RNA Polymerase III Transcription Initiation From Type 2 Promoter
Gene Ontology:
Molecular function: protein binding; RNA polymerase III general transcription initiation factor activity; DNA binding
Biological process: transcription initiation at RNA polymerase III promoter; 5S class rRNA transcription by RNA polymerase III; transcription by RNA polymerase III; tRNA transcription by RNA polymerase III
Cellular component: fibrillar center; nuclear membrane; nucleoplasm; nucleus; transcription factor TFIIIC complex
Genetic constraint (gnomAD): Loss-of-function variants: 30 observed, 41.39 expected, observed/expected ratio (o/e) 0.72, 90% interval 0.54 to 0.98. The upper end of that interval is the gene's LOEUF score, 0.98, which puts it in group 4 of 6, group 1 being the genes least tolerant of losing a copy. Missense variants: 399 observed, 542.4 expected, observed/expected ratio (o/e) 0.74, 90% interval 0.68 to 0.8. Synonymous variants: 155 observed, 181.96 expected, observed/expected ratio (o/e) 0.85, 90% interval 0.75 to 0.97.
Homologues: Orthologues: macaque GTF3C3 (99% identical), chimpanzee GTF3C3 (98% identical), dog GTF3C3 (96% identical), rabbit GTF3C3 (95% identical), pig GTF3C3 (95% identical), mouse Gtf3c3 (93% identical), rat Gtf3c3 (93% identical), guinea pig GTF3C3 (88% identical), tropical clawed frog gtf3c3 (80% identical), zebrafish gtf3c3 (66% identical), Drosophila melanogaster CG8950 (30% identical), Caenorhabditis elegans tftc-3 (27% identical).
Diseases named in the same sentence as GTF3C3 in open-access papers:
GTF3C3 is named in the same sentence as 10 diseases in open-access papers, as found by Europe PMC text mining. Sharing a sentence is not in itself a finding about the gene and the disease. The quoted sentences say what the papers report.
Intellectual disability (2 papers, 2024 to 2025). "In conclusion, this study further confirms the association of biallelic variants in GTF3C3 with an autosomal recessive neurodevelopmental disorder featuring intellectual disability, microcephaly, brain anomalies and in some cases seizures." (PMID 40040844, 2025).
microcephaly (2 papers, 2019 to 2025). A congenital or acquired developmental disorder in which the circumference of the head is smaller than normal for the person's age and sex. "Knockout of the GTF3C3 ortholog in zebrafish recapitulated the key clinical symptoms including microcephaly, brain anomalies and seizure susceptibility." (PMID 40040844, 2025). "In vivo studies of loss of function of gtf3c3 in zebrafish show in addition to microcephaly, an exacerbated motor response to PTZ and higher p-MAPK/ERK brain activity, features that are consistent with increased seizure susceptibility." (PMID 40040844, 2025). "Another study reported a patient with profound microcephaly, facial dysmorphism, and failure to thrive to harbor a homozygous splice site variant in GTF3C3 causing skipping of exon 10 and parts of exon 11 (in-frame deletion)." (PMID 30552426, 2019). "Functional analyses revealed that gtf3c3-knockout (KO) zebrafish display neurodevelopmental defects including microcephaly and seizures." (PMID 40040844, 2025).
epilepsy (1 paper, 2019). A brain disorder characterized by episodes of abnormally increased neuronal discharge resulting in transient episodes of sensory or motor neurological dysfunction, or psychic dysfunction. "Thus, we consider GTF3C3 as a candidate for neurodevelopmental disorders which may or may not include epilepsy." (PMID 30552426, 2019).
Obesity (1 paper, 2023). Accumulation of substantial excess body fat. "KSR1 has been reported to be related to the regulation of glucose homeostasis, and GTF3C3- to obesity-related dysglycaemia." (PMID 37204309, 2023). "Our study also identified several other genes, such as ZNF827, MIR7641-2, RAPTOR, KSR1, GTF3C3, and NFIC, whose role in obesity or obesity-related disorders has been consistently shown in previous studies." (PMID 37204309, 2023).
neurodevelopmental disorder (2 papers, 2019 to 2025). A behavioral and cognitive disorder with onset during the developmental period that involves impaired or aberrant development of intellectual, motor, or social functions. "GTF3C3 was classified as moderately confident candidate gene in a recently published study on neurodevelopmental disorders in consanguineous families after detection of homozygous missense variants in two affected sisters with a phenotype including mild ID, seizures, and dysmorphism." (PMID 30552426, 2019).
GTF3C3 also shares sentences with these, for which no sentence is quoted: Brain atrophy (1 paper); breast carcinoma (1); developmental delay (1); Failure to thrive (1); tumour (1).